CD4 (CD4 molecule)
Diseases named in the same sentence as CD4 in open-access papers (continued):
Sharing a sentence is not in itself a finding about the gene and the disease.
infection (continued). "Here, we show that the persistent intracellular pathogen Brucella abortus prevents immune activation of macrophages by inducing CD4+CD25+ T cells to produce the anti-inflammatory cytokine interleukin-10 (IL-10) early during infection." (PMID 23818855, 2013). "This suggests that HIV-1 trans infection of CD4+ T cells can occur via DC-SIGN-independent mechanisms." (PMID 24278768, 2013). "We also observed that T cell activation decreased at 22 days post-infection together with a strong decline of the Granzyme B-expressing CD4+ T cell population." (PMID 24367519, 2013). "As expected, anti-IL-12p40 mAb treatment of WSX-1−/− mice from day 7 of infection onwards significantly reduced both the proportion and the absolute number of T-bet expressing CD4+ T cells accumulating in the liver." (PMID 24244314, 2013). "Some of these models involve infection of activated CD4 T-cells that are allowed to return to a resting state through various culture conditions, with latency established in 1% to 75% of cells depending on the system." (PMID 23375003, 2013). "Twenty-four h after infection, the U87.CD4.CCR5 cells were extensively washed and trypsinized to remove residual adsorbed virus prior to further culture for 10 days." (PMID 23618462, 2013). "The recruitment of CD4 T cell subsets to the lungs after infection was also examined by flow cytometry in order to relate specific T cell subsets to protection." (PMID 23977248, 2013). "For instance, infection of BALB/c mice with Brugia pahangi third-stage larvae (L3) resulted in expansion of a population of CD4+CD25+ T cells which was highly enriched in Foxp3 and IL-10 gene expression." (PMID 23365718, 2013). "In NR4, both anti-NA antibodies and T cells specific for NRT1 antigens seemed to have worked for inhibition of virus propagation since both NI activity and IFN-γ-producing CD8+/CD4+ T cells against NRT1 were increased after challenge infection." (PMID 24376571, 2013). "The addition of RTS,S-induced CSP-specific CD4+ T cells was estimated to increase vaccine efficacy against infection to 40% (95% CI, 34%–48%)." (PMID 23613845, 2013). "Polyfunctional CD4 or CD8 T cells are proposed to represent a correlate of immune control for persistent viruses as well as for vaccine mediated protection against infection." (PMID 24146841, 2013). "HIV-1 infected, mature MDDC also activate CD4+ T cells, facilitating the process of trans infection." (PMID 24278768, 2013). "The viral set point is a major indicator of the course of disease following the end of the acute infection phase, and is highly correlated with the CD4+ count decay in the asymptomatic phase and with viral activity." (PMID 24302983, 2013). "To determine biological significance, we infected mice with Leishmania major, as pathogen clearance is highly dependent on IFNγ-producing CD4+ T cells at the infection site." (PMID 23991011, 2013). "This strongly indicates that CD4 T cells help B cells to produce neutralizing antibodies which seem to play a marginal role during the acute phase of infection but instead seem to be able to control MCMV replication during late stages of infection." (PMID 23717308, 2013). "Human immunodeficiency virus type 1 (HIV-1) infection of target cells requires CD4 and a co-receptor, predominantly the chemokine receptor CCR5." (PMID 24381033, 2013). "Our in vivo analysis on the other hand, indicates early immune recognition of CD4+ T cellular infection is compromised, possibly due to loss of HIV-specific CD4+ T cell help at primary infection, or that immune clearance is abrogated by persistent viremia." (PMID 23555209, 2013). "Consistent with experimental data, resistance begins to emerge after 50 days, with the K65R mutant dominating the viral population at a lower viral load and a higher CD4 count than WT infection due to the mutant’s reduced replicative capacity." (PMID 23379669, 2013).
infection (continued). "We found that long-lived HIV-infected CD4+ T cells contributed poorly to the total resting HIV reservoir in the PTCs because of a low rate of infection of naïve T cells and a skewed distribution of resting memory CD4+ T cell subsets." (PMID 23516360, 2013). "Upon infection the numbers of CD137+ CD4+ T cells rapidly increased in the bone marrow but we did not observe a similar increase in the number of CD137+ CD4+ T cells in 12 months old compared to 3 months old WT mice." (PMID 23945137, 2013). "Nevertheless, at day 7 upon infection some mice presented CD4+IFN-γ+ T cells at higher frequency than controls." (PMID 23937079, 2013). "We used a lower FV dose of 500 SFFU for this infection as it only served as a boost to make the CD4+ T cell response more readily detectable." (PMID 24349306, 2013). "It will also be important to study the CD4+ Th1 cells since they are particularly important to the development of acquired immunity against experimental infection in mice with protozoan parasites." (PMID 23527169, 2013). "HIV-1 depletes CD4+ T cells: on average, relative to uninfected donor-matched control tissues, HIV-1LAI.04 depleted 48.0±5.6% of CD4+ T cells after 9 days of infection." (PMID 23408885, 2013). "Patients starting therapy soon after infection, outside the setting of a randomized clinical trial, are more likely to have low CD4 cell counts and/or a more pronounced decline." (PMID 23724048, 2013). "These authors detected high levels of apoptosis among activated CD4+ T cells in BCG experimental infection." (PMID 24288555, 2013). "Understanding the consequences of CD4 independence in settings where it is acquired, therefore, provides insight into critical factors that maintain CD4 dependence in normal infection." (PMID 24219995, 2013). "Pearson correlation coefficients for CD4+ naive and memory cell subpopulations with biomarkers of inflammation, CVD risk, and infection." (PMID 24009662, 2013). "After larvae activate complement, vasoactive and chemotactic peptides (C3a and C5a) are generated, and these peptides mobilize eosinophils to the area of infection independently of specific mechanisms (CD4+ and IL-5)." (PMID 23509684, 2013). "In that study, clearance of secondary infection is obtained with very small numbers of initially available resident memory CD4+ T cells, compared to amounts required for resident memory CD8+ T cells." (PMID 23580062, 2013). "U87.CD4.CCR5 cells were used for dual-infection competitions pitting each chimeric Env virus against all others, in what was essentially a viral ‘round-robin’ tournament." (PMID 23638182, 2013). "Several groups have attempted to mimic in vitro the infection of activated CD4+ T cells, with HIV-1 or HIV-1 derived vectors, followed by the transition of these infected cells to a resting state to establish latency in memory CD4+ T cells." (PMID 23803414, 2013). "We also sorted naïve CD4+ T-cells from lymph node tissue from all five patients and the infection frequency of these cells ranged from 2376–2857 cells/HIV-1 DNA molecule (geometric mean of patients 1–5, columns 10–13)." (PMID 23818847, 2013). "Productive infection of CD4+ T cells was also significantly abrogated by 45 to 50% when cells were treated with the mAb α-LFA-1 68.5A5 (p < 0.05)." (PMID 23590845, 2013). "Flow cytometry at 4 d after infection showed that, whereas infection rates were similar between the 2 viruses, CD4 expression at the cell surface of PMBCs infected with H6R28LEP shCD4 was one tenth that of PBMCs infected with H6R28LEP." (PMID 23409116, 2013). "Nevertheless, in most infections, the precise mechanisms of CD4 T cell mediated protection remain uncertain." (PMID 23383106, 2013). "Although IMs make important contributions to innate immune defense during infection, recent studies also implicate IMs in priming of CD4 T cell responses during fungal, viral and parasitic infections." (PMID 24220507, 2013).
infection (continued). "For HIV-1BaL-infected lymphoid tissues, IL-7 increased Bcl-2 expression in HIV-1-infected CD4+ T cells 2.2±0.2 fold and 2.6±0.2 fold on day 6 and 9 post infection, respectively (n = 6, p<0.001)." (PMID 23408885, 2013). "While LCMV-specific memory populations can be easily tracked for over a year, the CD4 T cell memory responses in this Lm-infection model were difficult to measure reliably beyond D70 post-infection (LLO190 = 0.06% of CD4 T cells at D70 p.i.)." (PMID 23762323, 2013). "CD4+ T-cells and macrophages were treated with E2 prior to infection with HIVBaL after which secretion of RANTES and MIP-1β was analyzed." (PMID 23614015, 2013). "First, our deterministic ODE model shed some new light on CD4+ T cell distribution after infection as well as the role of PPARγ during infection." (PMID 24039925, 2013). "By hijacking the existing pathways of cell-to-cell communication, HIV-1 can evade certain stages of the humoral immune response and reach the final target of infection, namely, CD4+ T lymphocytes." (PMID 23590845, 2013). "In comparison to the uninfected control, all tested strains significantly up-regulated the total numbers of CD4+ T cells and NK cells at day 7 of infection, and the total numbers of CD8+ T cells at day 3 and 7 of infection (p≤0.05)." (PMID 23922974, 2013). "Given that blood-derived monocytes/macrophages express CD4 and CCR5, but not CXCR4, they are highly susceptible to R5 HIV-1, albeit with much lower production of infectious virus than cis infection of CD4+ T cells." (PMID 24278768, 2013). "In HIV-1LAI.04-infected lymphoid tissues, IL-7 25 ng/mL increased Bcl-2 expression in HIV-1-infected CD4+ T cells on average 2.3±0.1 fold and 2.4±0.1 fold on day 6 and 9 post infection, respectively (n = 8, p<0.0001)." (PMID 23408885, 2013). "Here we enter the complex world of HIV-1 cis infection of professional APC that is required for induction and maintenance of anti-HIV-1 CTL, as well as trans infection of CD4+ T cells." (PMID 24278768, 2013). "We observed thymic atrophy and subsequent CD4+CD8+ T cell depletion during the acute phase of infection in both strains of mice, as for previous reports." (PMID 23776551, 2013). "Recently, residues in gp41 including H625/T626 were found to increase CD4 independent infection, global neutralization sensitivity, and sensitivity of Env to cold inactivation." (PMID 23468626, 2013). "DC-SIGN allows for the capture of virus and its heightened transfer to CD4+ lymphocytes via trans-infection." (PMID 23874931, 2013). "We demonstrate that the major target cells for the virus, CD4+ T cells and macrophages, are present in macaques semen at all stages of infection." (PMID 24348253, 2013). "Although the gastrointestinal tract is often thought of as a large site of susceptible CD4+ T cells and an important site of HIV/SIV infection, this study indicates that it is at best a minor contributor to plasma viral load in early infection." (PMID 24119218, 2013). "In this infection model, CD4+ and CD8+ T cell derived IL-10 plays an essential role for the establishment of pathogen persistence." (PMID 24244162, 2013). "Altogether, these data suggest infection with HIV to have a major impact on lymphoid tissue despite the ability to preserve CD4+ T cell counts." (PMID 23696852, 2013). "This reduction in cell-to-cell adhesion also resulted in a marked decrease in the productive mDC-mediated HIV-1 trans-infection of primary CD4+ T cells." (PMID 23590845, 2013). "Immunization with recombinant RV16 VP0 protein increased the magnitude of airway T cell, especially CD4+ T cell, responses to infection consistent with the recruitment to and expansion of immunization-induced memory T cells in the airways." (PMID 24086140, 2013).
infection (continued). "It is possible that Prostratin induces changes to the viral receptor expression levels among activated CD4+ T-cells that can disrupt pseudotype entry, but the magnitude of change is too small to block infection with replication-competent virus." (PMID 23201205, 2013). "Our recent studies also revealed that LPS administration induced CD4+ T cell activation during SIVmac239 infection of Chinese RM (unpublished data)." (PMID 23947613, 2013). "Of particular relevance, Bim has been shown to mediate the loss of effector CD4+ and CD8+ T cells following antigen clearance during the contraction phase of the T cell response to several pathogenic infections." (PMID 23840678, 2013). "Regulatory T cells expressing CD4+/CD25+/FoxP3+ increased significantly over the course of infection." (PMID 23555767, 2013). "The mechanism of DC-mediated trans infection is extremely efficacious and can result in infection of multiple CD4+ T cells as these cells make exploratory contacts on the DC surface." (PMID 23593001, 2013). "In four of the five patients we found evidence for multiple infection (multiple HIV-1 DNA molecules in at least one row of 10 wells) of memory CD4+ T-cells from both lymph node tissue and peripheral blood and naïve T- cells from lymph node tissue." (PMID 23818847, 2013). "DC infected at these mucosal transmission sites likely spread HIV-1 through trans infection of regional CD4+ T cells." (PMID 24278768, 2013). "Only the number of CD4-positive cells increased at 14 days after infection in mice treated with celecoxib compared with infected mice." (PMID 23818746, 2013). "We demonstrated that all major viral target cells, including CD4+ T cells and macrophages are productively infected at every stage of infection." (PMID 24348253, 2013). "The three trajectories of the change in CD4 cell counts showed different rates of increase during the first week post-infection." (PMID 23409138, 2013). "This was demonstrated by the comparable data obtained with DC-mediated HIV-WT and HIV-ΔVpu transfer of infection to CD4+ T cells." (PMID 23311681, 2013). "Regardless of the route of transmission, the intestinal tissue, being a major site of viral replication, is rapidly affected by a conspicuous CD4+ T-cell depletion after primary infection." (PMID 23606583, 2013). "In the case of the strictly intestinal parasitic nematode H. polygyrus, rapid resolution of re-infection requires alternatively activated macrophages, CD4+ T cells, parasite specific type 2 antibody responses and B cell cytokine production." (PMID 24204255, 2013). "Infection with the human immunodeficiency virus-1 (HIV-1) causes a severe and selective depletion of CD4+ T lymphocytes in the immune system." (PMID 24047317, 2013). "Using the single-cell sequencing assay we analyzed the frequency of infection in memory and naïve CD4+ T-cells from both lymph node tissue and peripheral blood." (PMID 23818847, 2013). "These new tools reveal an unexpectedly complex CD4 T cell response to infection and a surprising role for B cells in preventing the spread of bacteria to multiple host tissues." (PMID 24204262, 2013). "The sterile alpha motif (SAM) and HD domain-containing protein-1 (SAMHD1) inhibits the infection of resting CD4+ T cells and myeloid cells by human and related simian immunodeficiency viruses (HIV and SIV)." (PMID 23874389, 2013). "Although the HIV-1 pseudoviruses are only capable of a single-cycle infection they use CD4 and CCR5 to enter cells identically to HIV and are an appropriate and accepted method for viral entry studies." (PMID 23840383, 2013). "The major HIV-1 target cells supporting viral replication are activated CD4+ T-lymphocytes, while other cell types such as primary monocytes, dendritic cells (DCs), and macrophages also contribute to initial infection and viral transmission." (PMID 24523981, 2013).
infection (continued). "In the NOD mouse thymus, effector CD4+ T cell numbers were reduced by infection, whereas regulatory T cell numbers were maintained." (PMID 23554993, 2013). "Using an acute experimental model, we observed changes inGR/PRLR cross-activation related with the survival of CD4+CD8+thymocytes during infection." (PMID 24324845, 2013). "Infection with PyL clearly increased the number of CD3+CD4+ and CD3+CD4- (almost CD8+) cells that expressed IFN-γ." (PMID 23527234, 2013). "While we have previously shown that IL-17–producing CD4+ T (Th17) cells were barely detectable in LCMV-DOC infection, it remains possible that IL-21 inhibits Treg cell expansion by regulation of IL-6." (PMID 23696736, 2013). "In this context CD4 T cells were mainly implicated to support CD8 T cell responses, especially during secondary infections, as well as in supporting B cells through their support of antibody class switch recombination and affinity maturation." (PMID 23717308, 2013). "Circulating monocytes and their tissue-transformed macrophages are APC that can mediate HIV-1 trans infection of CD4+ T cells similar to DC." (PMID 24278768, 2013). "In the current study, we elucidate the role of CD4+ regulatory T cells (Tregs) in suppressing the exocytosis pathway during an asymptomatic low-level infection." (PMID 24156479, 2013). "Identifying such signals will also help further characterize the role of gelsolin in HIV-1 fusion, entry and infection of CD4+ T lymphocytes in vivo." (PMID 23575248, 2013). "Herein, we show that transient ablation of IMs during infection prevents Mtb delivery to pulmonary lymph nodes, reducing CD4 T cell responses." (PMID 24220507, 2013). "Our results show a massive infection of all resting CD4 T cell subsets by this CCR5-restricted viral cluster, involving predominantly all memory CD4 T cell subsets but also TN cells." (PMID 23691172, 2013). "This fastest rate of CD4+ T cell depletion by HIV-1 WT virus most probably reflects the more rapid infection dynamic of these viruses relative to their ΔVpu counterparts." (PMID 24195843, 2013). "Previous exposure to infection with N. brasiliensis induces potent CD4 T cell immunity in the murine host and upon subsequent reinfection with the parasite, results in 90% fewer worms being able to migrate, mature, and develop to adults in the duodenum." (PMID 23518620, 2013). "In our model simulations, prior to infection, the mean CD4+ and CD8+ T cell speed is approximately 9 μm/min with a maximum of 25 μm/min and the average T cell motility coefficient is 75 μm2/min." (PMID 24244151, 2013). "Our findings also correlate with a study demonstrating the critical role of CD4+ Th1 cells after genital HSV-2 infection by timely recruitment of CD8+ T cells to the site of infection." (PMID 24068938, 2013). "In contrast, CA HIV RNA level in typical progressors was demonstrated by several studies to significantly increase during this phase of infection and to inversely correlate with the CD4+ T cell count." (PMID 23587031, 2013). "In these subjects, the development of phenotypically-verified CXCR4-using variants that were capable of entering primary CD4+ T-cells via CXCR4 was exceedingly rare, with such variants detected at advanced infection in only one subject." (PMID 23824043, 2013). "HIV-1 drives monocyte/macrophages towards an inflammatory phenotype following infection and/or through gp120/CD4 interaction." (PMID 23818854, 2013). "The response in RV-immunized mice was dominated by CD4+ T cells whose number was ∼10-fold greater than CD8+ T cells by day 6 post-infection." (PMID 24086140, 2013). "As Chlamydia is an obligate intracellular pathogen, IFN-γ production by CD4 Th1 cells is essential for protective immunity to primary and secondary infection." (PMID 24204262, 2013). "For LAI, the average time to reduce CD4+ T cells to 50% of total blood T cells was 21.6 ± 2.4 days post infection (dpi, n = 7)." (PMID 24172637, 2013).